PRMT1 (protein arginine methyltransferase 1)
Diseases named in the same sentence as PRMT1 in open-access papers (continued):
Sharing a sentence is not in itself a finding about the gene and the disease.
tumor (continued). "Additionally, PRMT1 is involved in promoting DNA damage repair, leading to the acquisition of antiapoptotic and drug-resistant characteristics in tumor cells." (PMID 38326807, 2024). "In addition to its involvement in numerous physiological processes and tumor progression through the methylation of various substrates, PRMT1 also plays a crucial role in innate immunity." (PMID 40018367, 2024). "Additionally, PRMT1 inhibition increased the number of tumor-infiltrating lymphocytes and promoted tumor PD-L1 expression in a cGAS-dependent manner." (PMID 40018367, 2024). "PRMT1 catalyzes asymmetric dimethylation of arginine and participates in substrate recognition, Gene Transcription, and Translation, Regulating Cellular Processes and Tumor Development." (PMID 39741976, 2024). "Moreover, furamidine treatment and PRMT1 knockdown strongly suppressed in vivo tumor growth of U87MG GSCs in a CAM model." (PMID 38474197, 2024). "The role of PRMT1 in regulating the tumor microenvironment has also been gradually recognized, although its potential involvement in promoting tumor angiogenesis remains an area of unknown research." (PMID 38326807, 2024). "Notably, in breast cancer, PRMT1 promotes tumor cell proliferation, tumorigenesis, and metastasis by methylating substrates such as H4, BRCA1, C/EBPα, EZH2, Progesterone Receptor (PR), PHGDH, and SRSF1." (PMID 40018367, 2024). "Because the cGAS/STING pathway is essential for anti-tumor immunity, we further determined whether PRMT1 is a rational target for immunotherapy." (PMID 37193698, 2023). "Importantly, it has been reported that PRMT1 displays the tumor suppressive function by methylating p14ARF to promote apoptosis upon genotoxic stress." (PMID 37005412, 2023). "Thus it is worth further in-depth investigation of PRMT1-focused combination therapy in boosting anti-tumor immunity, especially in an immune-competent condition in vivo." (PMID 37193698, 2023). "PRMT1 protein expression was significantly higher in GC samples than in NATs from human patients (n = 30, P = 0.010), with 70% of samples showing an increased PRMT1 level, while c-Fos was expressed in tumor tissue in approximately 73.3% of patients." (PMID 37564212, 2023). "IHC staining of the tumor xenograft tissue further demonstrated that silencing of PRMT1 to interfere with the interaction between PRMT1 and PGC-1α resulted in downregulated PGC-1α expression and the consequent growth inhibition of anoikis-resistant LMP1-positive NPC in vivo." (PMID 37803433, 2023). "Thus, combination therapy of PRMT1 inhibitor with anti-PD-1 antibody augments the anti-tumor therapeutic efficacy in vivo." (PMID 37193698, 2023). "In addition, PRMT1 governs spliceosome function, and PRMT1 inhibition boosts anti-tumor immunity through MHC-I-mediated neo-antigen presentation." (PMID 37193698, 2023). "Similarly, pharmaceutical inhibition of PRMT1 also increased mPD-L1 expression in these tumor cells." (PMID 37193698, 2023). "However, in tumor cells, PRMT1 negatively regulates cGAS activation by methylating cGAS at R133 in its N-terminus to prevent dimerization and suppress cGAS/STING signaling." (PMID 37928266, 2023). "Our study therefore defines the PRMT1/cGAS/PD-L1 regulatory axis as a critical factor in determining immune surveillance efficacy, which serves as a promising therapeutic target for boosting tumor immunity." (PMID 37193698, 2023). "Notably, the deletion of Prmt1 largely abrogated tumor growth in orthotopic transplants in syngeneic mice, an effect that was partially rescued by the re-expression of Prmt1." (PMID 37673892, 2023). "However, overexpression of R378A, which lost its ability to be methylated by PRMT1, resulted in more significantly changed metastasis-related protein levels and inhibited tumor cell migration and invasion rates." (PMID 35941115, 2022).
tumor (continued). "Similarly, PT1001B (PRMT1 inhibitor) enhances antitumor immunity by inhibiting PD-L1 expression on tumor cells, upregulating tumor-infiltrating CD8+ T lymphocytes." (PMID 36713412, 2022). "In some tumor types, PRMT1 is an important regulator of the immune checkpoint pathway." (PMID 36713412, 2022). "Notably, MS023 treatment reduced the ADMA mark of the xenograft tissue, suggesting that the reduction of tumor size coincides with disruption of the enzymatic function of PRMT1." (PMID 35578032, 2022). "In addition, PRMT1 can protect the tumor cells, which can induce macrophages to assist in immune escape." (PMID 36713412, 2022). "In vivo, PRMT1 knockdown significantly reduced tumor growth." (PMID 33440687, 2021). "By contrast, methylation of CEBPα by PRMT1 impairs its tumor-suppressive function." (PMID 34683150, 2021). "PRMT1-dependent methylation also inhibits the tumor suppressive function of some substrates." (PMID 34833023, 2021). "Indeed, the anti-tumor miR-503 suppressed the progression of HCC by targeting the protein arginine methyltransferase 1 (PRMT1) and the WEE1 G2 Checkpoint Kinase (WEE1) to block EMT in HepG2 cells." (PMID 34069740, 2021). "Besides, we confirmed the antitumor effect of PRMT1 inhibitor DCPT1061 in ccRCC cell-derived tumor xenograft (CDX) models as well as patient-derived tumor xenograft (PDX) models." (PMID 33859753, 2021). "Moreover, PRMT1 inhibition by DCPT1061 not only inhibited tumor growth but also sensitized ccRCC to sunitinib treatment in vivo by attenuating sunitinib-induced upregulation of LCN2-AKT-RB signaling." (PMID 33859753, 2021). "However, limited studies focus on the role of PRMT1 in mediating histone methylation throughout tumour progression in patients with ESCC." (PMID 31043582, 2019). "PRMT1 phosphorylation at Y299 is common in tumours and was shown to alter PRMT1 target specificity." (PMID 31235809, 2019). "B upper panel, overexpression of PRMT1 significantly enhanced tumour growth (6 weeks)." (PMID 31043582, 2019). "The role of PRMT1 in tumorigenesis is still controversial and seems to depend on tumor type." (PMID 31655611, 2019). "However, ccRCC samples with nuclear grade II and lower tumor stages (I and II), had higher PRMT1 mRNA expression level." (PMID 31655611, 2019). "In addition, we observed a tendency to decrease in PRMT1 mRNA expression level along with the increase of tumor size." (PMID 31655611, 2019). "PRMT1 expression was associated neither with aberrant ß-catenin expression nor with N- cadherin gain or E-cadherin loss in analyzed tumor types." (PMID 31655611, 2019). "Taken together, we could suggest that the regulation of CDKN1A in HCC by several effector genes including PRMT1 can influence tumor growth." (PMID 29383172, 2017). "However, the roles of PRMT1 in apoptosis in other cells, especially non-tumor cells, were barely explored." (PMID 28671608, 2017). "Antitumor agents combined with a PRMT1 inhibitor may be an effective strategy for overcoming tumor MDR." (PMID 26934120, 2016). "Notably, PRMT1’s role in modulating tumor stemness and immune suppression suggests that its inhibition may synergize with immunotherapies by reactivating antitumor immune responses." (PMID 40927753, 2025). "Functionally, PRMT1 promotes tumor growth and confers CBP resistance across multiple preclinical models, including HNSCC cell lines, CDX, PDO, PDX, and Prmt1cKO mouse models, suggesting that targeting PRMT1 in combination with CBP could be a promising therapeutic strategy." (PMID 40270464, 2025). "Finally, we performed Western blot analysis to assess ADMA/MMA levels in the collected tumors, aiming to confirm whether the rescue of tumor growth is because of the catalytic activity of PRMT1." (PMID 40675804, 2025). "Recently, PRMT1 has indicated that PRM1 may have oncogenic function in tumor cells." (PMID 40612681, 2025).
tumor (continued). "Additionally, integrating demethylating agents like decitabine with PRMT inhibitors (targeting PRMT1) could reverse tumor suppressor gene silencing and inhibit metastasis pathways." (PMID 41219748, 2025). "Additionally, PRMT1 has been identified as a potential target for tumor therapy." (PMID 38605214, 2024). "Moreover, inhibitors of the PRMT1/SLC7A11 axis could delay tumor progression in CRC with low LPCAT2 expression, making it a potentially effective treatment for CRC." (PMID 38605214, 2024). "PRMT1 could accelerate tumor progression and metastasis via STAT3 signaling pathway in HCC." (PMID 37725627, 2023). "Thus, we hypothesized that PRMT1-mediated HBP1 methylation may participate in PRMT1-induced metastasis in tumor cells." (PMID 35941115, 2022). "Thus, PRMT1-catalyzed ADMA is required across multiple PDAC models to maintain tumor growth." (PMID 34330913, 2021). "Indeed, we found that PRMT type I inhibition with MS023 and PRMT1-specific inhibition with TC-E5003 severely impaired growth of Apc-deficient tumor organoids but not normal organoids." (PMID 33575256, 2020). "Hence, PRMT1 seemed to be an effective target for overcoming tumor MDR." (PMID 26934120, 2016). "Upon entering the tumor cells, DCLX069 was rapidly released from the DNM in response to elevated intracellular GSH levels, leading to a robust modulation of the PRMT1/SOX2 axis." (PMID 41377018, 2025). "IHC staining was also performed on the subcutaneous tumor tissue to analyze the expression of TRIM21, PRMT1, and Ki-67." (PMID 39890802, 2025). "Upon entering the tumor cells, DCLX069 is rapidly released from the DNM due to high intracellular GSH levels, leading to swift regulation of the PRMT1/SOX2 axis." (PMID 41377018, 2025). "Clinical data analysis revealed a strong correlation between high levels of PBX2, PRMT1, SMARCC1, and IGF2BP2 with poor prognosis and tumor progression in HNSCC patients." (PMID 40270464, 2025). "Only the oligomeric form was capable of rescuing tumor growth in PRMT1-depleted PDAC models, directly linking PRMT1’s structural state to its tumor-promoting function and highlighting the therapeutic potential of targeting its oligomeric assembly." (PMID 40675804, 2025). "Recently, Wang reported that PRMT1 activates related pathways by recruiting MLXIP to the promoter region of β-catenin and thus plays a role in promoting tumor cell growth and metastasis." (PMID 40858547, 2025). "Our initial findings show that PRMT1 overexpression significantly enhances TNBC cell proliferation, underscoring its role in promoting tumor growth." (PMID 40927753, 2025). "In GC, the knockdown of PRMT1 suppresses the cGAS/STING pathway, leading to the generation of type I interferon and facilitating M1‐like macrophage polarization within the tumor microenvironment." (PMID 41256732, 2025). "In summary, our findings revealed that PRMT1 knockdown inhibits the cGAS/STING pathway in GC, which produces type I IFNs to promote the polarization of M1-like macrophages in the tumor microenvironment." (PMID 40858547, 2025). "Recent study advancements have underscored the function of PRMT1 in augmenting the activity of PHGDH via methylation, thereby facilitating serine production and demonstrating tumor‐promoting effects on HCC in both in vitro and in vivo studies." (PMID 41256732, 2025). "Therefore, manipulating PRMT1 may be a viable strategy for modulating the tumor microenvironment." (PMID 40858547, 2025).
tumor (continued). "Preclinical studies have shown that dual inhibition of PRMT1 and PRMT5 can produce synergistic tumor suppression, but the broader consequences of disrupting such interactions on normal tissue homeostasis require further investigation." (PMID 40791817, 2025). "The expression of PRMT1, PRMT3, PRMT4, PRMT5, and PRMT7 was elevated in tumor samples compared to normal tissue, while PRMT2, PRMT8, and PRMT9 were decreased." (PMID 40399547, 2025). "We showed that PRMT1 is crucial for enhancing the migration and invasion of TNBC cells, key factors in tumor spread and metastasis." (PMID 40927753, 2025). "PRMT1-depleted PANC-1 cells, rescued with various oligomeric forms, were transplanted into immunocompromised mice, and tumor growth was monitored after tumor establishment." (PMID 40675804, 2025). "In the context of CRC, the NO pathway metabolites are found to be altered, with enzymes such as ARG1, PRMT1, and PRMT5 being overexpressed in both tumor and tumor-adjacent tissues." (PMID 41268067, 2025). "KTN1 binds PRMT1 and prevents its degradation, thereby potentiating β‐catenin signaling; suppressing the cGAS–STING pathway to sustain a “cold‐tumor” phenotype." (PMID 41256732, 2025). "Functional studies demonstrate that PRMT1 regulates IGF2BP2 expression, which in turn mediates PRMT1‐driven oncogenic effects, including tumor proliferation, apoptosis resistance, and CBP sensitivity." (PMID 40270464, 2025). "Consistent with the association between PRMT1/5 and the DDR signature, significant positive correlations between PRMT1/5 and ERCC1 mRNA expression levels were observed in primary tumor specimens from the TCGA cohort." (PMID 38826355, 2025). "In contrast, the LN229R group with concurrent FOSL1 knockdown and PRMT1 overexpression demonstrated accelerated tumor progression in comparison to the group featuring FOSL1 knockdown, PRMT1 overexpression, and CAPS knockdown." (PMID 41423530, 2025). "For instance, inhibition of PRMT1 or treatment with PRMT1 inhibitors (e.g., AMI-1, C7280948) increases tumor sensitivity to the EGFR monoclonal antibody cetuximab and to PARP inhibitors such as olaparib." (PMID 41204384, 2025). "In HCC, elevated PRMT1 expression is inversely correlated with the infiltration of CD8+ T cells and macrophages within the tumor microenvironment, suggesting an immunosuppressive role." (PMID 41256732, 2025). "Both PRMT1 and PRMT5, members of the protein arginine methyltransferase (PRMT) family, play crucial roles in tumor development." (PMID 40393971, 2025). "Pharmacological inhibition or genetic knockout of PRMT1 restores STAT1 signaling and MHC-I levels, thereby enhancing anti-tumor immunity and improving responsiveness to immune checkpoint blockade." (PMID 41359051, 2025). "To determine if TRIM21 functions in a PRMT1-dependent manner, we restored the expression of PRMT1 in the OE-TRIM21 group, which reversed the tumor-inhibiting effect of TRIM21." (PMID 39890802, 2025). "To further validate the observation, we analyzed the expression of PRMT1, PRMT4, and PRMT6 in fresh frozen lung tumor tissue and found elevated expression of all three PRMTs in tumor tissue compared to adjacent uninvolved tissue." (PMID 38303720, 2024). "This suggests that targeting the PRMT1-cGAS-STING signaling pathway, in conjunction with immune checkpoint inhibitors, is a potentially effective strategy in tumor immunotherapy." (PMID 40018367, 2024). "Here, we provide a comprehensive description of the two key signaling components, PRMT1 and cGAS, in the PRMT1-cGAS-STING signaling pathway for therapeutic intervention to augment anti-tumor immunity." (PMID 40018367, 2024). "PRMT1 was also responsible for promoting the Wnt and Notch pathways in ESCC, leading to increased tumour initiating cells with enhanced self-renewal capabilities and resistance to cisplatin treatment." (PMID 39703687, 2024).
tumor (continued). "The PRMT1-cGAS-STING pathway is a critical signaling axis in the innate immune response and has significant potential in enhancing anti-tumor immunity." (PMID 40018367, 2024). "Our research has found that both inhibitors and or knockdown of PRMT1 can increase PD-L1 expression and significantly improve the anti-PD1 therapy in various mouse tumor models." (PMID 40018367, 2024). "Through pharmacological inhibition of PRMT1 with MS023, we observed a significant suppression of MM tumor growth in vivo." (PMID 37600810, 2023). "In line with this, modulation of the RBP network by PRMT1 inhibition reveals a unique vulnerability in Myc-high PDAC patient organoids and markedly reduces tumor growth in male mice." (PMID 37673892, 2023). "Corroborating these results, using human scRNA-seq data, we show that PRMT1 is also upregulated in PDAC cells compared to normal ducts and that its expression increases with tumor stage; however, how it contributes to tumor progression is not fully understood." (PMID 37673892, 2023). "PRMT1 and BCL2L12, the top two upregulated regulators of S‐CC, also play critical roles in tumor development." (PMID 36637997, 2023). "In the context of Neu-induced carcinogenesis, overexpression of PRMT1 and PRMT6 significantly accelerated breast tumor onset, while CARM1 increased tumor progression only at tumorigenesis." (PMID 35311114, 2022). "Subsequently, we utilized PRMT1 mutant G98R, which has lost its enzymatic activity, to test its role in HBP1 methylation and tumor cell metastasis and growth." (PMID 35941115, 2022). "For example, PRMT1 and PRMT2 are overexpressed in GBM and their depletion was shown to decrease tumor cell proliferation in mouse xenografts." (PMID 36425564, 2022). "Inhibition of PRMT1 in mice led to the inhibition of IL6 signaling and downstream STAT3 activation and decreased the number of tumor cells and M2 type macrophages." (PMID 36713412, 2022). "We knocked out the expression of Prmt1, Ripk1 or Axl in a murine MC38 tumor cell line by gRNA-expressing vectors compatible with either Perturb-seq or CROP-seq." (PMID 36518525, 2022). "In the present study, we demonstrate that HBP1 can be methylated by PRMT1 at R378, which alleviates HBP1-mediated repression of tumor metastasis and growth through regulation of GSN expression." (PMID 35941115, 2022). "Both groups have independently reported that the combination of PRMT1 and PRMT5 inhibition has synergistic effects on tumour cell growth, at least partly mediated by methylthioadenosine phosphorylase (MTAP)." (PMID 33404912, 2021). "HMT, such as protein arginine N-methyltransferase 1 (PRMT1) and MYND domain containing 3 (SMYD3), have been described to favor M2 polarization and, as such, represent targets to inhibit accumulation of tumor-promoting TAM." (PMID 33859645, 2021). "Our data demonstrate that PRMT1 coordinates the expression of key genes involved in the regulation of cell cycle progression, DNA replication, and DDR, required to maintain tumor growth and to promote genomic stability." (PMID 34330913, 2021). "Compared to normal mucosa, ARG1, PRMT1, and PRMT5 were overexpressed in both tumor and tumor-adjacent tissue and DDAH2 solely in tumor-adjacent tissue." (PMID 32932854, 2020). "Kaplan–Meier survival analyses revealed that PRMT1, ZEB1, nuclear grade, and tumor stage were significant prognostic factors in ccRCC." (PMID 31655611, 2019). "The significant heterogeneity of PRMT1, ZEB1, and TWIST1 immunostaining was observed among analyzed tumor types (p < 0.001)." (PMID 31655611, 2019). "We found that the expression levels of PRMT1, PRMT2, PRMT4, and PRMT6 are positively correlated with the tumor grades." (PMID 30382083, 2018). "In summary, PRMT1 is a central regulator of immune response, inflammation regulation, and tumor immune escape, achieved by methylating diverse nonhistone substrates and finely regulating key immune signaling pathways such as cGAS–STING, NF‐κB, and MHC‐II." (PMID 41256732, 2025).